PPARG (peroxisome proliferator activated receptor gamma)
Diseases named in the same sentence as PPARG in open-access papers (continued):
Sharing a sentence is not in itself a finding about the gene and the disease.
Candida infection (2 papers, 2010 to 2023). "On the other hand, PPARG can also protect against excessive inflammation and tissue damage caused by an uncontrolled immune response to Candida infection in humans." (PMID 38003833, 2023). "PPARG can modulate immunity to candidiasis in different ways." (PMID 38003833, 2023). "The involvement of Dectin-1 in improving the resolution of candidiasis by PPARγ ligands is in line with our results which showed for the first time that the increase in Dectin-1 cell surface expression by IL-13 was mediated by the PPARγ signaling pathway." (PMID 20062524, 2010).
carbohydrate metabolism disorders (2 papers, 2022 to 2024). "The aim of the present study was to explore the association of polymorphisms within MC4R, PPARG, and TCF7L2 with the risk of different carbohydrate metabolism disorders and changes in the body composition in overweight or obese patients with early carbohydrate metabolism disorders." (PMID 35292917, 2022).
clear cell renal cell cancer (2 papers, 2020 to 2026). "In clear cell renal cell carcinoma, ACLY expression is upregulated through HIF-2α/LPCAT1/FBXW7 and VHL/PPARγ axes, promoting lipid synthesis, tumor proliferation, and metastasis." (PMID 41958067, 2026).
cystic kidneys (2 papers, 2020). "Pioglitazone; a well-known anti-diabetic drug that is a peroxisome proliferator-activated receptor gamma (PPAR-γ) agonist, has been found to suppress the development of renal cyst in the preclinical studies via different mechanisms which inarguably suggests its pleiotropy." (PMID 33308138, 2020).
demyelination (2 papers, 2023). "The remyelination-enhancer effect was consistent incuprizone-induced demyelination model in a completely PPARγ-agonistic pathway that disappears incase of PPARγ knockout." (PMID 37893218, 2023).
dysferlinopathy (2 papers, 2020 to 2025). "Accordingly, a human dysferlinopathy myoblast cell line, cultured under conditions that promote myogenic differentiation, has been shown to manifest aberrant adipogenic commitment, as indicated by PPARγ expression." (PMID 41155239, 2025).
eosinophilia (2 papers, 2005 to 2013). "Recent studies demonstrated that PPARγ agonists reduce AHR, eosinophilia and Th2 cytokine and chemokine levels." (PMID 24040386, 2013).
esophageal tumor (2 papers, 2010 to 2022). "Another study has reported the reduced expression of PPARγ in esophageal tumor lesions and proved that ESCC cell proliferation could be inhibited by efatutazone, a PPARγ agonist, by inactivating the PI3K–Akt and MAPK pathways." (PMID 36142861, 2022).
Ewing sarcoma (2 papers, 2017 to 2022). A small round cell tumor that lacks morphologic, immunohistochemical, and electron microscopic evidence of neuroectodermal differentiation. "Metastatic osteosarcoma (P = 0.031) and Ewing Sarcoma (P = 0.0002) tumors expressed significantly higher level of PPARγ protein compared to non-metastatic tumors." (PMID 35922782, 2022).
fibromyalgia (2 papers, 2022). A chronic disorder of unknown etiology characterized by pain, stiffness, and tenderness in the muscles of neck, shoulders, back, hips, arms, and legs. "Pioglitazone, one of the other primary hits, has been shown to be a PPARg agonist that significantly improved skeletal muscle functions in a reserpine‐induced fibromyalgia rat model." (PMID 35411556, 2022).
gallstones (2 papers, 2025). Solid crystalline precipitates in the biliary tract, usually formed in the gallbladder, resulting in the condition of cholelithiasis. "Studies suggest that activating PPARγ can reduce the production of pro-inflammatory cytokines and suppress inflammatory pathways, including NF-κB, which are implicated in gallstone development." (PMID 40166468, 2025).
giant cell tumor (2 papers, 2019 to 2024). A benign, intermediate, or malignant tumor that arises from the bone or soft tissue.
glomerular disease (2 papers, 2015 to 2022). "However, the specific variant or isoform(s) expression of PPARγ and the role of its AS in podocytes and glomerular disease is unexplored." (PMID 36359851, 2022). "Traditional agonists (e.g., pioglitazone) and selective modulators (e.g., GQ-16) of peroxisome-proliferator-activated-receptor-γ (PPARγ) reduce proteinuria in animal models of glomerular disease and protect podocytes from injury via PPARγ activation." (PMID 36359851, 2022). "Earlier these effects of PPARγ in influencing non-diabetic glomerular disease was thought to be through its anti-inflammatory actions on endothelial and myeloid cells." (PMID 36359851, 2022).
granulosa cell tumor (2 papers, 2018 to 2025). A slow-growing, malignant tumor, characterize by the presence of granulosa-like cells and Call-Exner bodies, that is almost always found in the ovary. "Previous studies have revealed increased PPARγ expression in granulosa cell tumors." (PMID 40519257, 2025).
hepatitis C (2 papers, 2019 to 2022). "Therefore, PPARγ agonists have been proposed to alleviate these symptoms and delay hepatitis C deterioration." (PMID 31614690, 2019). "Despite the promising results, clinical development of PPARγ agonists for hepatitis C was stopped when new and more potent pharmacotherapy, direct-acting antivirals, was approved by the FDA in 2011 for hepatitis C treatment." (PMID 31614690, 2019).
hypercortisolism (2 papers, 2017 to 2023). "Two further female patients were diagnosed with FPLD1 following the exclusion of hypercortisolism and pathogenic PPARG variants." (PMID 28973478, 2017). "This therapeutic effect was independent of the actions of ACTH, postulating a promising application of PPARG activation in endogenous hypercortisolism." (PMID 38098864, 2023).
Hyperoxaluria (2 papers, 2016 to 2019). Increased excretion of oxalates in the urine. "Therapeutic effects of the PPARα agonist fenofibrate and PPARγ agonist pioglitazone were also assessed in a 1% ethylene glycol-induced rat model of hyperoxaluria." (PMID 27022389, 2016).
hypertrophic cardiomyopathy (2 papers, 2022 to 2025). A condition in which the myocardium is hypertrophied without an obvious cause. "In this study, our PPI network results revealed that PPARα, PPARγ, and CREB1 were the potential targets of C. reticulata with higher relevance for combating hypertrophic cardiomyopathy." (PMID 40832599, 2025).
hypoadiponectinemia (2 papers, 2012 to 2016). "Decreased PPARγ phosphorylation and increased PPARγ expression induced by PP treatments was responsible for preventing hypoadiponectinemia, thereby allowing adequate adiponectin signaling (increased β-oxidation, insulin sensitivity and glucose uptake; decreased gluconeogenesis)." (PMID 27367676, 2016).
ileitis (2 papers, 2012 to 2020). "Based on SAMP1/YitFc animal example, developing a spontaneous ileitis due to a defect of expression of PPARγ in ileal crypts, the polymorphisms of PPARγ has been tested in CD." (PMID 22997506, 2012).
intervertebral disc degeneration (2 papers, 2018 to 2024). "Giving the role of PPARγ in glucose metabolism and the role of high glucose in intervertebral disc degeneration, we supposed that the high glucose condition induces autophagy via PPARγ-dependent pathway in our present study." (PMID 29686698, 2018). "But up to now, PPARγ has never been reported in the NP cells and in intervertebral disc degeneration in previous literature." (PMID 29686698, 2018).
intestinal cancer (2 papers, 2019 to 2025). "Taken together, our findings demonstrated that PPARγ mediates the effects of Wnt/β-catenin signaling in regulation of ketogenesis in the intestinal cancer cell lines LS174T and Caco2." (PMID 31546785, 2019). "In summary, we showed that HMGCS2 expression and βHB concentration are regulated by the Wnt/β-catenin/PPARγ pathway in human intestinal cancer cell lines and mouse intestinal organoid cultures." (PMID 31546785, 2019). "Our results demonstrate that inhibition of Wnt/β-catenin signaling increased, while activation of Wnt/β-catenin pathway decreased, the expression and transcriptional activity of PPARγ, but not PPARα, in intestinal cancer cell lines." (PMID 31546785, 2019).
leiomyosarcoma (2 papers, 2017 to 2023). An uncommon, aggressive malignant smooth muscle neoplasm, usually occurring in post-menopausal women. "Furthermore, the same study group underlined that the activation of the cell membrane angiotensin receptor 2 provoked human leiomyosarcoma cell differentiation and apoptosis in a PPARγ-dependent manner." (PMID 37298140, 2023).
liver dysfunction (2 papers, 2014 to 2023). "While PPARγ has historically been studied in adipose tissue, laboratories have shown that gain- and loss-of-function of PPARγ in the liver exacerbates and ameliorates diet-induced liver dysfunction, which is mediated, in part, by Cidec." (PMID 37797918, 2023).
magnesium deficiency (2 papers, 2017 to 2021). A nutritional condition produced by a deficiency of magnesium in the diet, characterized by anorexia, nausea, vomiting, lethargy, and weakness. "PPARG becomes a functional nutritional disease-associated protein because these phenotypes (altered insulin level, high low-density lipoprotein, and abnormal blood pressure) are potential phenotypes for various nutritional diseases." (PMID 29258237, 2017).
male infertility (2 papers, 2024 to 2025). The inability of the male to effect fertilization of an ovum after a specified period of unprotected intercourse. "PPARγ could be potentially modulated by its natural or artificial ligand, affording new therapeutic opportunities for a potential treatment for male infertility, increasing the performance of spermatozoa." (PMID 40001905, 2025). "Thus, further molecules and factors might be involved in the relationship between of PPARγ and LPO in male infertility." (PMID 40001905, 2025).
MELAS (2 papers, 2017 to 2020). "Apart from many targets including PINK1, FOXO1, PPARγ and Apaf-1 investigated before, MKNK2, GREM1 and EEF1A1 that might be potential targets of miR-27b-3p were revealed in the regulatory network of MELAS pathogenesis." (PMID 28139706, 2017).
mesothelioma (2 papers, 2022). A usually malignant and aggressive neoplasm of the mesothelium which is often associated with exposure to asbestos. "Using two intrapleural models, we identified PPARα and PPARγ as potential regulators of an invasion-associated gene expression signature in mesothelioma." (PMID 34984327, 2022). "Because we identified PPARα and PPARγ as potential regulators of a transcriptional program underlying the invasive and proliferative behavior of mesothelioma in the pleural space, we hypothesized that antagonizing these regulators would alter tumor cell invasion and proliferation." (PMID 34984327, 2022). "Although our results show that dual targeting of PPARα/γ is not an effective treatment strategy for mesothelioma, we note that genetic deletion of PPARγ may reduce invasion and proliferation of tumors in vitro." (PMID 34984327, 2022). "We observed a significant increase in proliferation, but only in the HAP1 parental cell line, not in the PPARA/PPARG KO cells (p. value <0.0001), suggesting that arachidonic acid induced increased mesothelioma cell proliferation in a PPARα- and PPARγ-dependent manner." (PMID 34984327, 2022).
metastatic cancer (2 papers, 2007 to 2023). A carcinoma which has spread from the original site of growth to another anatomic site.
migraine (2 papers, 2025). "PPARα and PPARβ/δ appear to be involved in migraine resolution through their anti-inflammatory activities and PPARγ is involved in migraine onset." (PMID 40630421, 2025). "The authors suggest that PPARα and PPARβ/δ serve in a protective role during migraine and that the reduction of PPARγ accelerates migraine." (PMID 40630421, 2025). "PTGS2, PTGS1, PPARG, ADRB2, GABRA1, and NOS3 are potential targets for the treatment of migraines using ginkgo seeds due to their advantageous values." (PMID 41009787, 2025). "Moreover, molecular docking results demonstrated that these core components have a strong affinity with multiple target proteins such as PTGS2, PPARG, BCL2, CASP3, TNF, and ESR1, suggesting that ginkgo seeds exert their therapeutic effects on migraines through multiple targets and pathways." (PMID 41009787, 2025).
MODY (2 papers, 2021). "Consequently, recent studies identified RFX6 as a novel MODY gene and WFS1, PPARG, and GLIS3 have recently been proposed as potential candidates for these rare MODY forms." (PMID 34079523, 2021).
myeloid leukemia (2 papers, 2018 to 2020). A clonal proliferation of myeloid cells and their precursors in the bone marrow, peripheral blood, and spleen. "Given that APL cells have a low level of endogenous PPARγ protein, PPARγ expression was stably depleted in non-APL myeloid leukemia cells, and the effects of these cells on the liver and serum lipid levels were examined in the mice." (PMID 32929351, 2020). "Non-APL myeloid leukemia cells induced no liver TG or TC enhancement over time in vivo, but PPARγ knockdown cells increased both the liver TG and TC levels of the transplanted mice." (PMID 32929351, 2020). "PPARγ agonists (e.g., PGZ) have also been suggested as potential modulators in myeloid leukemia by activating the transcriptional activity of target genes that control apoptosis and differentiation as well as by downregulation of the STAT5-driven quiescence of the leukemic stem cell pool." (PMID 30542286, 2018). "Furthermore, reactivation of KLF4 expression through modulation of PPARγ signaling, exerted a multifaceted tumor-suppressive effect in CDX2 positive myeloid leukemia cell lines and primary AML blasts, suggesting PPARγ agonists as a therapeutic modality in a large proportion of AML patients." (PMID 30542286, 2018).
nematode infection (2 papers, 2018 to 2021). "The role of PPARG, DUOX2 and IL5RA genes in relation to the immune response has been previously reported in different nematode infection studies." (PMID 29703268, 2018). "In mice, high expression of the PPARG gene was found in response to nematode infection and the mice lacking the PPARG gene were unable to mount protective immune response to nematode infection." (PMID 29703268, 2018).
nephrosis (2 papers, 2022). Pathological processes of the KIDNEY without inflammatory or neoplastic components. "Consistently, a few studies have shown increase in nephrosis just after 3 weeks with e.g., podocyte-specific deletion of PPARγ when challenged with ADR in mice on C57BL/6J background." (PMID 35784478, 2022).
optic neuropathies (2 papers, 2013 to 2019). "The results suggest that endogenous PPARγ plays an intrinsic role in the progression of traumatic optic neuropathies." (PMID 23874818, 2013).
oral squamous cell carcinoma (2 papers, 2002 to 2020). "PPARG has also been suggested as a potential therapeutic target gene for oral squamous cell carcinoma, and the activation of PPARG was shown to downregulate several features of the neoplastic phenotype in human upper aerodigestive tract tumors." (PMID 32373170, 2020). "We recently showed that the non-steroidal anti-inflammatory drug (NSAID) sulindac induces cell growth inhibition and apoptosis in human oral squamous cell carcinoma (SCCa) cells, accompanied by upregulation of the mRNA and protein expression of PPARγ." (PMID 12454768, 2002). "Our results provide the first evidence of significant antineoplastic effects of 15-PGJ2 on human oral squamous cell carcinoma cells, which may be related to downmodulation of Stat3 and are at least partly mediated through PPARγ-independent events." (PMID 12454768, 2002). "However, the possible effects of PPARγ agonists on human oral squamous cell carcinoma have not yet been reported." (PMID 12454768, 2002).
pancreatic adenocarcinoma (2 papers, 2012 to 2025). "Besides, immunohistochemical staining of resected specimens by means of a polyclonal PPARγ antibody has evidenced PPARγ protein expression in the nuclei of carcinoma cells in 90% of human pancreatic adenocarcinomas." (PMID 22966223, 2012).
Peri-Implantitis (2 papers, 2019 to 2021). An inflammatory process with loss of supporting bone in the tissues surrounding functioning DENTAL IMPLANTS. "Further studies need to address the detailed mechanism of PPARγ activation on bone loss of peri-implantitis." (PMID 34401982, 2021). "Adipogenic event is activated on peri-implantitis affected tissue: expression of peroxisome proliferator activated receptor gamma (PPARG) and insulin (INS), which regulates fatty acid storage, glucose metabolism and adipogenesis by fat cells, was detected and it is up regulated." (PMID 31242601, 2019).
relapsing remitting MS (2 papers, 2010 to 2020). "In this study, we demonstrate that the expression of PPARγ is decreased in monocytes of relapsing-remitting MS (RR-MS) patients and that MS-associated proinflammatory cytokines IFNγ and IL1β reduce PPARγ expression." (PMID 33297574, 2020). "PPARγ agonist pioglitazone was tested as an add-on therapy with interferon-β in a small cohort of relapsing remitting MS (RRMS) patients." (PMID 21234105, 2010). "We demonstrate that monocytes of relapsing-remitting MS patients display a marked decrease in PPARγ expression, while the expression of PPARα and LXRα/β is not altered." (PMID 33297574, 2020).
Renal angiomyolipoma (2 papers, 2009 to 2026). "Finally, renal angiomyolipomas from patients with tuberous sclerosis complex contain both adipose and smooth muscle-like components with activated mTORC1 signaling and elevated PPARγ expression." (PMID 19593385, 2009).